USP7 (ubiquitin specific peptidase 7)
Diseases named in the same sentence as USP7 in open-access papers (continued):
Sharing a sentence is not in itself a finding about the gene and the disease.
tumor (continued). "Three stable cell strains with knockdown of USP7, hnRNPA1, or lncFERO were constructed by using lent-viruses containing shRNAs, and then the cell strains were used for subcutaneous tumor implantation." (PMID 34845198, 2021). "Exosomes containing circRNAs secreted by adipocytes promote tumor growth and reduce DNA damage by inhibiting miR-34a and activating USP7/cyclin A2 signaling pathway." (PMID 34031263, 2021). "Since USP7 has crucial roles in generating anti-tumor drug resistance, numerous studies have been conducted to pharmacologically inhibit its deubiquitinating activity from avoiding abnormal stabilization or trafficking of its substrates." (PMID 33967786, 2021). "The deubiquitinating enzyme ubiquitin specific peptidase 7 (USP7) is overexpressed in a variety of tumor tissues and is closely related to the poor prognosis of patients." (PMID 33869059, 2021). "Previous studies have demonstrated that USP7 plays a prominent role in tumor development and progression." (PMID 33869052, 2021). "Collectively, our findings showed that abnormal serine metabolism stabilized YAP through USP7 to activate the Hippo pathway output, which stimulated tumor cell proliferation." (PMID 34055773, 2021). "Longer OS was observed in tumor-bearing mice transplanted with USP7-KD, hnRNPA1-KD, and lncFERO-KD cells." (PMID 34845198, 2021). "This section will enumerate examples of USP7’s involvement in anti-tumor therapy resistance to demonstrate USP7 as a biomarker for the phenomenon of tumor resistance and an important prognostic indicator for tumor therapy." (PMID 33967786, 2021). "As a result, USP7 can mediate the chemoresistance of taxanes by regulating mitosis progression, and the inhibition of USP7 helps to enhance the taxane sensitivity of tumor cells." (PMID 33967786, 2021). "Unexpectedly, the USP7 KO cells displayed an advanced cell proliferation and tumor growth in the xenograft murine model." (PMID 34580281, 2021). "USP7 plays an important role in tumorigenesis and progression by deubiquitinating a variety of tumor regulatory molecules and is a promising target for the development of lead compounds." (PMID 33498168, 2021). "The ubiquitin-specific protease 7 (USP7), as a deubiquitinating enzyme, plays an important role in tumor progression by various mechanisms and serves as a potential therapeutic target." (PMID 33869052, 2021). "We explored the effects of targeting USP7 on TAMs and anti-tumor immunity in vivo, using a subcutaneous Lewis tumor-bearing mouse model." (PMID 32802195, 2020). "Taken together, we provided in vivo evidence to demonstrate that USP7/hnRNPA1 promotes exo-miR-522 secretion from CAFs, decreasing lipid-ROS levels in tumors and facilitating tumor growth." (PMID 32106859, 2020). "Inhibition of USP7 by the chemotherapeutic inhibitor HBX19818 and siRNA-mediated downregulation of USP7 resulted in significant increases in tumor-cell apoptosis and disruption in homologous recombination repair due to genotoxicity." (PMID 32354135, 2020). "Nevertheless, our study identifies ECT2 as an essential regulatory scaffolding protein in controlling the function of USP7, and indicates that ECT2/USP7 circuit is critically implicated in breast carcinogenesis." (PMID 32929379, 2020).
tumor (continued). "Together, these data demonstrate that USP7 has context-dependent tumor suppressor and oncogenic roles and that up- or down-regulation can contribute to carcinogenesis." (PMID 32850836, 2020). "Given the link between upregulation of USP7 and tumor aggressiveness in MM, an alternate therapeutic approach of using USP7 inhibitors would represent a major advance." (PMID 32354135, 2020). "Although outside the scope of this review, USP7 likely also contributes to carcinogenesis by regulating a number of tumor suppressors and oncogenes with roles outside of direct genome stability maintenance." (PMID 32850836, 2020). "Ubiquitin-specific peptidase 7 (USP7), the seventh identified DUBs14, is a robust tumor enhancer due to its deubiquitination of N-Myc15 or MDM2 that results in the inactivation of P5316." (PMID 33040080, 2020). "ALOX15, one of the key genes leading to ferroptosis, showed a sharp decrease, while the levels of USP7 and hnRNPA1 were clearly increased in tumor tissues." (PMID 32106859, 2020). "USP7 is able to remove the monoubiquitin moiety from PTEN, causing PTEN’s exclusion from the nucleus, thereby inhibiting the nuclear-associated tumor suppressor function of PTEN." (PMID 32560247, 2020). "This has been exploited for finding inhibitors of the DUB Usp7, for example, which show efficacy in tumor models." (PMID 32033280, 2020). "Correlatively, tumor sphere dissemination calculations of MCF7 demonstrated that USP7 inactivation decreased tumor dissemination by 42% after p5091 treatment and 32% after USP7 knockdown." (PMID 32922122, 2020). "The inhibited expression of USP7, hnRNPA1 and miR-522 prolonged the survival period of tumor-bearing mice, and the mice in the cisplatin groups had a better survival compared with mice treated with saline." (PMID 32106859, 2020). "Altogether, these results suggest that targeting USP7 can significantly promote polarization of TAMs into M1 MΦs and activate the anti-tumor immune responses mediated by CTLs in the TME in vivo." (PMID 32802195, 2020). "Our data show that expression of HUWE1, USP9X and USP7 are higher in the tumor and metastatic lesions of many patients, compared to matched normal tissue irrespective of their mutational status." (PMID 32345963, 2020). "This is the first study reporting that the anti-apoptotic MCL-1 protein stability is regulated by the deubiquitinase USP7 in tumor cells (arsenic and BaP co-exposure-transformed cells)." (PMID 32802178, 2020). "The knockdown of USP7, hnRNPA1 or miR-522 in CAFs observably suppressed tumor growth and enhanced sensitivity to cisplatin, but up-regulated Lipid ROS levels in tumors." (PMID 32106859, 2020). "In ESCC cells downmodulation of USP7 expression decreases tumor proliferation, impairs cell migration and invasion and induces the expression of pro-apoptotic genes (e.g., NOXA)." (PMID 32560247, 2020). "In summary, targeted inhibition of USP7 combined with anti-PD-1 can exert a synergistic effect on the Lewis subcutaneous tumor." (PMID 32802195, 2020). "This study provides the first evidence showing that the anti-apoptotic MCL-1 protein stability is regulated by the deubiquitinase USP7 in tumor cells (arsenic and BaP co-exposure-transformed cells)." (PMID 32802178, 2020). "Up to now, USP7 is the most widely studied deubiquitinating enzymes, and is considered as an oncogene by promoting tumor growth and negatively affecting the patient immune response to tumors." (PMID 31114498, 2019).
tumor (continued). "In a word, USP7 affects tumor progression by interacting with FOXOs and affecting their activity and localization." (PMID 31114498, 2019). "The CCDC6 and USP7 expression was evaluated semi-quantitively on 46 bladder cancer tumor samples; each tumor sample was present in duplicate in our TMA and analysed blindly by two pathologists (left)." (PMID 30786932, 2019). "In a nutshell, USP7 can be considered as a Wnt activator for tumor-specific therapeutic target for most CRCs." (PMID 31114498, 2019). "As a consequence, USP7 can be considered as a drug target to modulate C-Myc and N-Myc amount in order to block tumor development." (PMID 31114498, 2019). "In fact, a study in 2013 showed that aberrant USP7 overexpression decreases Foxp3 polyubiquitination and protects it from proteasome degradation, resulting in Treg-cell-mediated suppression and tumor growth." (PMID 31114498, 2019). "And the exosome circRNAs, secreted from liver adipocytes, promoted tumor growth by controlling miR-34a level and activating the USP7/CCNA2 signaling pathway." (PMID 31886176, 2019). "Blocking USP7 facilitates the E3 ligase MdM2 degradation, and by doing so the USP7 inhibitor controls the tumor growth significantly." (PMID 30344943, 2018). "To validate the tumor-suppressive effect of USP7 inhibitors, we repeated the xenograft experiment by comparing tumor growth between the parental and USP7 CRISPR-targeted SW480 cells." (PMID 29045831, 2017). "Previously, we reported the P5091 series of small molecule USP7 inhibitors and demonstrated their direct anti-tumor activity in vivo using xenograft models." (PMID 29236775, 2017). "Overall, in this study we utilized CLL cell lines and primary tumor cells as models to investigate the USP7 role in CLL and to demonstrate the efficacy of a small molecule inhibitor P5091, in this disease." (PMID 28418900, 2017). "USP7 depletion in APC-mutated CRC inhibits Wnt activation by restoring β-catenin ubiquitination, drives differentiation, and suppresses xenograft tumor growth." (PMID 29045831, 2017). "Our data not only clarify the tumor-specific role of USP7 in Wnt signaling but also highlight the importance of developing physiological experimental models such as CRISPR-engineered mutations for molecular and functional studies." (PMID 29045831, 2017). "Inactivation of USP7, either by CRISPR mutation or by small-molecule inhibitors, suppresses APC-mutated CRC tumor growth and Wnt activation by restoring β-catenin ubiquitination." (PMID 29045831, 2017). "Our data highlight the potential of USP7 as a tumor-specific drug target for CRCs carrying CID-deleted APC mutations." (PMID 29045831, 2017). "Consistent with the inhibitor data, USP7 depletion significantly inhibited tumor growth, compared to the parental SW480 tumors with reduced Wnt target gene expression." (PMID 29045831, 2017). "In this study, we identified USP7 as a tumor-specific target by characterizing the fundamental Wnt-activating mechanism of APC mutation." (PMID 29045831, 2017). "Together, our data suggest that USP7 can be used as a tumor-specific therapeutic target to suppress tumor growth and induce cellular differentiation via Wnt inactivation." (PMID 29045831, 2017). "We show that USP7-mediated β-catenin deubiquitination is a tumor-specific event when APC is truncated and that it is RNF220 independent." (PMID 29045831, 2017). "Pharmacological inhibition of USP7 is therefore a promising strategy for suppressing Treg functions and promoting anti-tumor immunity." (PMID 29236775, 2017).
tumor (continued). "In line with these considerations, we have here observed that USP7 promotes PTEN delocalization in CLL samples, favoring the loss of its nuclear tumor suppressive functions." (PMID 28418900, 2017). "On the other hand, incomplete KO of USP7 was sufficient to inhibit Wnt signaling and suppress tumor growth." (PMID 29045831, 2017). "USP7 expression in PC has been correlated with tumor aggressiveness and has been considered as a possible therapeutic target." (PMID 28415632, 2017). "Our data demonstrate that USP7 is responsible for PTEN nuclear exclusion with consequent impairment of its tumor suppressive functions and that USP7 inhibition restores PTEN nuclear pool and its oncosuppressive activity in the context of CLL." (PMID 28418900, 2017). "For instance, targeting USP7 in the oncology context would be a good therapeutic strategy; however we need to very carefully consider the possible effects of inhibiting USP7 on the inflammatory response to the tumour." (PMID 27597804, 2016). "USP7 upregulation was detected in 11 out of 12 tumor tissues compared with their normal counterparts." (PMID 25519684, 2015). "USP7 expression positively correlated with a more advanced tumor stage (p < 0.001), lymph node metastasis (p = 0.006), and bigger tumor size (p = 0.038)." (PMID 25519684, 2015). "FOXO 3a and 4 are deubiquitinated by USP7, to be retained in the nucleus to promote their tumor suppressive transcriptional activity." (PMID 25121098, 2014). "Simultaneously, USP7 regulates metabolic adaptation by maintaining lipid homeostasis, redox balance, ferroptotic resistance, and nutrient stress responses, thereby supporting tumor survival under adverse conditions." (PMID 42245660, 2026). "It is essential to first ascertain whether STS suppressed USP7 expression in tumor cells and to understand the subsequent impact on the susceptibility of these cells to T cell-mediated cytotoxicity." (PMID 40365281, 2025). "Additionally, xenograft proliferation was used to explore the effect of USP7 on tumor growth in animals." (PMID 40061891, 2025). "In vivo, Usp7-cKO suppressed tumor growth and improved prognosis." (PMID 40365281, 2025). "Additionally, transfection of HCT8 cells with specific shRNAs targeting USP7 or treatment of RKO cells with the USP7 inhibitor P5091 significantly inhibited tumor volume growth and weight, which was largely reversed in the context of DACH1 overexpression." (PMID 40389405, 2025). "However, despite extensive research, the exact role of USP7 in providing a metabolic advantage to tumor cells remains controversial." (PMID 41157055, 2025). "Furthermore, research suggests that overexpression of USP7 in human tumors inhibited tumor cell cycle arrest and promoted apoptosis, thereby promoting tumor progression." (PMID 40006058, 2025).
tumor (continued). "Above results let us make a hypothesis that knockdown of USP7 can suppress GC tumor growth in vivo, the ability of USP7-knockdown cells to affect tumor growth was detected in xenograft model bearing Con and USP7 KD MKN45 cells." (PMID 40061891, 2025). "Therefore, USP7 overexpression enhances the Treg cell-mediated immune suppression and finally leads to tumor growth and proliferation." (PMID 41157055, 2025). "Future research could investigate the mechanisms of CAFs in other tumor types and assess the potential clinical applications of USP7, hnRNPA1, and miR-522." (PMID 40485724, 2025). "This functional divergence informs distinct therapeutic strategies: interventions targeting OTUB1 prioritize immunomodulation and migration inhibition, whereas USP7-focused therapies aim to restore tumor suppressor function and block pro-proliferative signaling." (PMID 40469292, 2025). "Moreover, in head and neck esophageal carcinoma, the migration and proliferation of tumor cells are mediated by a complex pathway that deeply involves USP7." (PMID 41157055, 2025). "Treatment with the USP7 inhibitor P5091 significantly delayed tumour progression in KPC mice." (PMID 41463025, 2025). "USP7 pharmacological inhibition suppresses the proliferation of CRC by inducing apoptosis only on cells carrying a mutated CID, suggesting that USP7 acts as a tumor-specific drug target." (PMID 41157055, 2025). "Similarly, overexpression of USP7 significantly promoted tumor proliferation in SW480 cells, while targeted knockdown of DACH1 negated this promotional effect." (PMID 40389405, 2025). "Suppression of TRIM21 antagonized tumor suppression induced by USP7 downregulation." (PMID 38702792, 2024). "Abrogation of VEGF secretion from fibroblasts in response to USP7 inhibition resulted in inhibition of tumor neoangiogenesis and increased tumor recruitment of CD8‐positive T‐lymphocytes, leading to significantly improved sensitivity to immune checkpoint inhibitors." (PMID 38602256, 2024). "Consistent with the in vitro findings, USP7 knockdown suppressed the tumor growth in the mice." (PMID 39406703, 2024). "Finally, future research also needs to further explore the possible application of USP7 in tumor treatment." (PMID 39767641, 2024). "The nude mice were sacrificed at 3 weeks after injection, tumours were photographed and their weights were analyzed, showing that the shUSP7 group had smaller tumours while the shUSP7shDICER group almost completely reverse the tumour‐suppressing effect of USP7 knockdown in vivo." (PMID 37867415, 2024). "Moreover, the intratumor microvascular density was analyzed by IHC staining of an endothelial cell marker CD31, and the results showed that USP7 depletion impaired angiogenesis within the tumor." (PMID 39406703, 2024). "USP7 knockdown hindered the inhibition of tumor proliferation induced by ShTRIM21." (PMID 38702792, 2024). "In addition, USP7 inhibitors can suppress tumor angiogenesis and increase the effectiveness of immune checkpoint inhibitors by downregulating VEGF secretion in fibroblasts." (PMID 39767641, 2024). "Consequently, USP7 inhibitors enhanced the anti-tumor effects of PARP inhibitors in an FBP1-dependent manner." (PMID 39048965, 2024). "USP7, also known as herpesvirus-associated ubiquitin-specific protease (HAUSP), is a member of the USP subfamily of deubiquitinases that plays a crucial role in various tumor types." (PMID 38474186, 2024). "Inhibition of USP7 significantly suppresses tumor growth in HNSCC xenografts and PDX models." (PMID 38983924, 2024).